HMOX1 (heme oxygenase 1)
Diseases named in the same sentence as HMOX1 in open-access papers (continued):
Sharing a sentence is not in itself a finding about the gene and the disease.
tumor (continued). "Hmox1 had mRNA expression lower in the tumor than in the normal tissue by gene array." (PMID 27999449, 2016). "The ratio of Hmox1/Nrf2 mRNA levels in the tumor tissue may reflect a difference in their transcriptional regulation and was a negative predictor for distant metastasis in CRC." (PMID 27999449, 2016). "Heme oxygenase 1 (Hmox1) plays an important role in the growth and spread of tumor, and its expression is regulated positively by Nrf2 [nuclear factor (erythroid-derived 2)-like 2; NFE2L2] and negatively by kelch-like ECH-associated protein 1 (Keap1) and by BTB and CNC homology 1 (Bach1)." (PMID 27999449, 2016). "The Hmox1/Nrf2 mRNA ratio in the tumor tissue may be a useful indicator for distant metastasis in CRC." (PMID 27999449, 2016). "Hmox1 may counteract reactive oxygen species- (ROS-) mediated carcinogenesis, but its overexpression provides tumor cells with an aggressive survival advantage." (PMID 27999449, 2016). "Without Bach1 expression, Keap1 may become the major regulator of Hmox1 mRNA transcription in CRC tumor tissue." (PMID 27999449, 2016). "Heme oxygenase 1 (Hmox1) can be induced by oxidative stress and may play a role in tumor induction, growth, or spread." (PMID 27999449, 2016). "NQO1 overexpression induced tumor cell proliferation via the up-regulation of cyclins and was accompanied by an increase in other antioxidant enzymes, such as HMOX-1 and GST, providing tumors with increased protection against cytotoxic agents allowing for rapid cancer progression." (PMID 28983331, 2015). "The induction of HMOX1 by let-7 might potentiate anti-proliferative effects of let-7 on cancer cells while decreasing inflammatory responses that often accompanies tumor development." (PMID 25669981, 2015). "To determine if FABP4, IL-1β, and HMOX-1 are involved in tumor cell adaptation to adipocyte-derived factors, we cultured PC3 cells in media containing gradually increasing amounts of Adipo CM (gradient of 5-25% over multiple passages) and then maintained them long-term in 25% Adipo CM." (PMID 24240026, 2013). "Moreover, transient up-regulation of Hmox1 in all tested cell lines corroborates with the inhibitory effects of mastic oil on tumor-related inflammatory response." (PMID 20003503, 2009). "Consequently, HMOX1 pathway activation may hinder antitumor CD8+ T‐cell function in the tumor microenvironment (TME)." (PMID 37031459, 2023). "Therefore, it is reasonable to hypothesize that miR-873-5p may serve as a tumor suppressor in GBM with the involvement of HMOX1, HIF1α and SPOP." (PMID 37382594, 2023). "Building on this understanding, we postulated that HMOX1 expression within a comprehensive tumor gene expression data set could serve as a marker for investigating the influence of microhemorrhage on the development of CD163+ and SPP1+ TAMs, which are implicated in tumor progression." (PMID 38060331, 2023). "Thus, miR-873-5p-mediated inhibition of HMOX1 may represent a useful target for inhibiting GBM tumor progression." (PMID 37382594, 2023). "Therefore, our findings indicated ferroptosis induction by CTX through the activation of the NRF2/HMOX-1 pathway, which might provide a potential strategy for tumor chemotherapy." (PMID 35264971, 2022). "Thereafter we suspect that HMOX1 might influence the malignant properties and patient outcomes by intervening immune infiltration in the TME, as it was significantly associated with tumor purity, immune checkpoints’ levels, immune infiltration abundance, as well as immune-oncological pathways." (PMID 34858984, 2021). "Thus, to perceive how skin allergen exposure modulates the basal levels of Hmox1 gene in neuronal cells, the N2a-wt and N2a-APPwt cells were incubated in the absence or in the presence of skin allergens, for 3 and 6 h, and the mRNA levels were analyzed by real-time RT-PCR." (PMID 33096789, 2020). "However, most experiments support a permissive role of HMOX1 in tumor growth." (PMID 32010627, 2019).
tumor (continued). "In addition, heme degradation by HMOX1 in tumor cells seems to support cancer by counteracting oxidative stress during tumorigenesis and upon anti-tumor therapies, but concomitantly to promote TAMs acquisition of a M1-like phenotype, favoring tumor regression and increased drug sensitivity." (PMID 32010627, 2019). "Moreover, HMOX1 activity may affect anti-tumor therapies, as its expression is further elevated in response to radio-, chemo-, or photodynamic therapy and is involved in resistance to them." (PMID 32010627, 2019). "Analysis of the microarray data for the FAP+ TAM population isolated from 4T1 tumours revealed that these cells were also directly expressing some of the acute wound inflammatory response genes, including Il1b, Il6 and Osm, alongside the phenotypic markers Hmox1 and Fap." (PMID 30054470, 2018). "Compared with C-MOs, MAMPCs expressed higher levels of TAM signature genes (i.e., Arg1, Cdh1, Hmox1, Il1r2, Mrc1, and Stab1) that were also highly expressed by MAMs, suggesting that differentiation of C-MOs to MAMPCs (M-MDSCs) is directed toward the tumor-promoting macrophages." (PMID 29387063, 2017). "However, a central role of heme oxygenase 1 (HO-1) has been demonstrated in tumour progression and the ability to counteract oxidative stress has been related to the antioxidant and antiapoptotic properties of its metabolic products bilirubin, ferritin and carbon monoxide." (PMID 27023064, 2016). "However, a recent review highlighted a different function for HMOX1 in tumor progression." (PMID 26588813, 2016). "Solasodine triggers ferroptosis by upregulating HMOX1 while suppressing GPX4 and SLC40A1, markedly inhibiting tumor growth." (PMID 41373599, 2025). "In our study, HMOX1 was found to interact with PTGDS and mediate the tumor promoting role of PTGDS in PTCL through promoting iron metabolism and autophagy-dependent ferroptosis." (PMID 39706989, 2025). "IP, HERPUD1, GADD34, HMOX1, and MANF mRNA levels were significantly upregulated in tumor samples, indicating robust activation of all three arms of the UPR." (PMID 41120732, 2025). "Consistent with our proposed mechanism of study, β‐elemene and imatinib co‐treated tumours showed concomitant increases in NRF2, HMOX1 and 4‐HNE staining." (PMID 40866937, 2025). "Here, we found that inhibiting PPARγ in OSCC can promote ferroptosis by upregulating HMOX1 and promoting disulfidptosis through the upregulation of SLC7A11 and the subsequent recruitment of additional cDCs and CD8+ T cells to inhibit tumor development." (PMID 38786003, 2024). "Further studies found that heme oxygenase-1 (HO-1), triggered by HIF-1α, scavenges intracellular ROS from SP and inhibits the differentiation of tumor cells, leaving patients with a poor prognostic outcome." (PMID 37588219, 2024). "Conversely, the downregulation of LHPP, HMOX1, and BCL2 disrupt tumor-suppressive functions, oxidative stress management, and apoptotic processes, respectively." (PMID 39468431, 2024). "HMOX1, p-NRF2, and SLC7A11 were expressed at higher levels in the GW9662-treated tumor tissues than in the control tumor tissues." (PMID 38786003, 2024). "Especially, the therapeutic mechanisms were resolved, where inhibiting mitochondrial pathway and activating AKT signaling pathway including AKT-1, HMOX-1 and NRF-2 were found to be responsible for the excellent anti-tumor consequences." (PMID 39014402, 2024). "Beyond it, we further stained the tumor sections with AKT-1, HMOX-1 and NRF-2 antibodies to examine their expression." (PMID 39014402, 2024). "As expected, HMOX1 and TGFB1 were upregulated in tumor and the related ROC curves showed the great performance of prediction." (PMID 37653101, 2023). "Meanwhile, Rbfox3 and SFRTM2 levels were downregulated while the levels of the fibrosis markers HGF, HMOX1, ELN, and GREM1 were upregulated in the tumor microenvironment of NEPC." (PMID 37240308, 2023).
tumor (continued). "ThyroidPrint® is a novel q-PCR-based ten-gene classifier with its signature representing both the tumor microenvironment (CXCR3, CXCL10, CCR3, CCR7, and CXADR) and tumor epithelial cells (TIMP1, CLDN1, KTR19, AFAPL2, and HMOX1)." (PMID 37671897, 2023). "HMOX1 can be expressed in a variety of cells within the TME, including both malignant tumor cells and stromal cell populations, such as macrophages, dendritic cells and regulatory T cells." (PMID 36536381, 2022). "The high correlation of HMOX1 with CD86 and PDCD1 LG2 also suggests that interactions between tumor cell ferroptosis and immune cells need to be studied in more detail." (PMID 34975326, 2022). "The staining intensity of these two genes (HMOX1, ADM) in tumor cells is higher than in normal pneumocytes." (PMID 35957802, 2022). "Given that miR-24-3p inhibition leads to increased apoptosis, we predict that HMOX1 and PRSS8 function as tumor suppressors in CRC." (PMID 36457077, 2022). "The tumor-bearing animals treated with resveratrol showed increased apoptosis via STAT3 signaling and nuclear factor-like 2 (Nrf2)/heme oxygenase-1 (HO-1) pathway reduction." (PMID 35805049, 2022). "After analysis of 44 normal tissues and 520 primary tumor tissues of HNSCC from the TCGA database, and we found a lower expression level of HMOX1 mRNA in tumor tissues than normal tissues." (PMID 35682782, 2022). "Previous studies have indicated that the inhibition of HMOX1 reversed tumor EMT and impaired the invasion and migration of tumor cells." (PMID 36033490, 2022). "Then, we picked out 8 HAIRGs (VEGFA, CTNNB1, PPARG, HSP90AA1, HMOX1, LGALS3, SPP1, and RAC1) from the 17 HAIRG model through the LASSO Cox regression, upregulated genes accounted for 7/8 in tumor tissue, which was shown by a heat map." (PMID 35069936, 2022). "The diversity of stimuli which induce HMOX1 gene expression highlight the fundamental role of this enzyme within inflammation and stress responses which are exploited in the TME to facilitate tumor progression." (PMID 33868304, 2021). "MiR-1304, usually regarded as a tumor suppressor, inhibited non-small cell lung cancer (NSCLC) cell growth through suppressing heme oxygenase-1 (HO-1) and was down-regulated in NSCLC samples." (PMID 33593435, 2021). "Among these, JMJD1A was found to regulate a subset of hypoxia-induced genes, ADM, EDN1, HMOX1, and GDF15, and was important for the growth of tumour xenografts in a hypoxic environment." (PMID 34572020, 2021). "SLC7A11 was found to be expressed at high levels in tumor samples from KICH, KIRC, and KIRP, with upregulation of HMOX1 occurring in KIRC and KIRP." (PMID 35360452, 2021). "The pan-cancer expression profiles of SLC7A11, HMOX1, and MT1G were subsequently analyzed by integrating tumor samples in TCGA with normal samples in GTEx using the rank-sum test." (PMID 35360452, 2021). "Heme oxygenase 1 (HO1) is an antioxidative and cytoprotective enzyme inducing chemo‐resistant AML and has been focused as an immune checkpoint molecule in tumor microenvironments." (PMID 32670766, 2020). "Moreover, the re-expression of linc-PINT and HMOX1 is observed upon treatment of ALL with epigenetic drugs, and therefore, it may be one of the molecular mechanisms induced by these drugs to cause anti-tumor effects in this disease." (PMID 29560114, 2018). "In vitro, Reg3g upregulated EGFR in DCs, activated heme oxygenase-1 (Hmox1) involved JAK2/STAT3 signaling, raised levels of Th2 cytokines in and suppressed maturation of DCs, and enhanced tumor cell proliferation." (PMID 28880262, 2017). "In gene expression studies of SRC transformed by several cells, the genes IL8/CEF4, VIP, HMOX1, PLCPI, and UPP1 were identified as signature SRC aggressive tumor genes." (PMID 28945796, 2017).
tumor (continued). "Podgorski and colleagues demonstrated that lipids can be trafficked between adipocytes and cancer cells fuelling tumour growth and invasiveness by upregulating FABP4, IL-1β and HMOX-1 in the metastatic tumour cells." (PMID 27761371, 2016). "Here, we provided specific evidence for accumulation of marrow fat cell-supplied lipids by tumor cells, and demonstrated that the accelerated growth and invasiveness involves upregulation of tumor-derived FABP4, IL-1β and HMOX-1." (PMID 24240026, 2013). "The net effect of NO on tumor growth or apoptosis depends not only on its source and relative levels but also on the degree of activation of HIF1-α, heme oxygenase-1 (HO-1) and VEGF in the tumor microenvironment." (PMID 23964349, 2013). "Besides, Nrf2 regulates ferroptosis in tumor cells by inducing the expression of NQO1, HMOX1, and FTH1." (PMID 40530331, 2025). "The selection of Heme oxygenase-1 (HMOX1) and the enzyme 6-phosphofructo-2-kinase/fructose-2,6-biphosphatase 4 (PFKFB4) as therapeutic targets is grounded in their pivotal roles in promoting tumor progression and treatment resistance." (PMID 40739397, 2025). "Through transcriptomic profiling and protein–protein interaction (PPI) network analysis, we identified a subset of ferroptosis-related genes such as MAPK1, HMOX1, and TP63 that exhibit potential involvement in tumor progression, oxidative stress regulation, and immune interaction." (PMID 40868287, 2025). "Analysis of tumor tissues revealed no significant changes in Hmox1 expression or the frequency of HO-1+ TAMs." (PMID 40627458, 2025). "Furthermore, HMOX1 exerts extensive immune-regulatory roles within the TME, overall suppressing anti-tumor immune responses." (PMID 39850572, 2024). "The results showed that the knockdown of key genes (HMOX1, STEAP3, and LTF) combined with TMZ treatment significantly decreased both tumor volume and tumor weight compared to the group treated with TMZ alone, indicating an effective restoration of sensitivity to TMZ therapy." (PMID 37545464, 2024). "We also quantified the expressions of a ferroptosis marker gene PTGS2 and NRF2 downstream genes HMOX1 and TFRC in tumor tissues and found their expressions were all elevated by IKE treatment in mice received a control diet, but not in mice receiving methionine-free diet." (PMID 37553341, 2023). "Furthermore, compared to the normal tissue, the HMOX1 and TGFB1 expression level in tumor tissue are mostly different in 33 tumor types." (PMID 37653101, 2023). "Meanwhile, others found an increase in activity, for instance, in increased heme oxygenase-1 enzyme (HO1); however, this could play a role in enhancing the cell survival of tumor cells against oxidative injury." (PMID 38139811, 2023). "Hmox1 is expressed in numerous cell types present in the TME, such as malignant tumor cells, macrophages, dendritic cells, and regulatory T-cells, and contributes to tumor progression through various mechanisms." (PMID 37958903, 2023). "Similarly, compared to that in peritumor tissues, the expression of ferroptosis-inducing genes, including PTGS2, HMOX1, TFR2, and NCOA4, was down-regulated in tumor tissues, whereas ferroptosis-suppressor genes SLC7A11 and FTH1 were upregulated." (PMID 37554285, 2023). "In addition, a significant induction of ferroptosis-related genes (Ptgs2, Alox15 and Hmox1) was detected in tumor samples after treatment with RSL3 + iron, thus confirming the activation of the ferroptotic process inside the tumor mass." (PMID 36872341, 2023). "Zfp36, HMOX1, and ATF3 have antioxidant effects and play important roles in tumor progression." (PMID 36835629, 2023). "Furthermore, expression of miR-873-5p was increased, but that of HMOX1, HIF1α, and SPOP was reduced in the tumor tissue of mice treated with miR-873-5p agomir + oe-NC." (PMID 37382594, 2023).
tumor (continued). "Under the surviving stress upon TKIs, elevated METTL7B in LUAD cells accelerated the scavenging of excessive ROS in tumor microenvironment by upregulating the protein levels and enzymatic activities of three antioxidant enzymes GPX4, SOD1 and HMOX1 by m6A modification in their mRNAs." (PMID 35144642, 2022). "Furthermore, accumulation of ROS, which correlates with tumor aggressiveness, due to oxidative stress or hypoxia within TME leads to the upregulation of heme oxygenase 1 (HO-1) expression in DCs and TAMs." (PMID 36244976, 2022). "In addition, cellular transporters (Slc7a11) and detoxifying enzymes (Hmox1), induced in Apc wt organoids by mild CAP treatment, were expressed at significantly higher levels in basal conditions in tumor organoids." (PMID 35169122, 2022). "As the tumor grade increased, DPP4, HMOX1, and TFRC expression levels also increased." (PMID 35154262, 2021). "JMJD1A increases or maintains expression of certain genes under hypoxia by reducing H3K9 demethylation of specific hypoxia-responsive promoters, including ADM, EDN1, HMOX1, and GDF15, resulting in increased expression of these genes and favouring tumour cell growth." (PMID 34572020, 2021). "We had previously reported restoration of obstructed tumor blood flow by using NO donors, L-Arg, NG, and HU, and micellar forms of CO donors such as SMA/CORM2 and PEG-hemin or an inducer of heme oxygenase-1 (HO-1), which also generates CO." (PMID 34071552, 2021). "Furthermore, FRGs, IRGs, DEGs, and genes in the blue module were intersected, and seven hub genes (JUN, TNFAIP3, NOX4, HMOX1, SOCS1, CYBB, and TFRC), related to both ferroptosis and tumor immunity, were obtained." (PMID 35174170, 2021). "There were also genes that are of insignificant expression in tumor cells that increase in expression in KO cells, e.g. THBS3, IL2RG, SPRR3, TGM2, HMOX1 and TMEM62 or are lower in expression in tumor cells and significantly decreased in KO cells such as MAN1A1, CES1, STCBP6, SIVA1 and TMEM40." (PMID 31797958, 2019). "Non-significant differences were observed among treatments in the tumor growth nor in HMOX1, BCLXL, IKBA, and MKI67 gene expression." (PMID 30813528, 2019). "In this setting, FAP+ TAMs, which highly expressed Hmox1, were exclusively populating the 4T1 and not the E0771 tumours." (PMID 30054470, 2018). "Lycopene inhibited UVA/B induced overexpression of heme oxygenase-1 (HO-1), an indicator of oxidative stress, and also decreased UVA/B induced overexpression MMP-1, a metalloproteinase involved in the breakdown of collagen and skin photoaging." (PMID 29998107, 2018). "Here, we demonstrated a miRNA-induced dual regulation of heme oxygenase-1 (HO-1) via seed region and non-seed region, consequently inhibited tumor growth of NSCLC." (PMID 28749936, 2017). "In the absence of detectable Bach1 mRNA expression, the mRNA levels of Keap1, but not Nrf2, retained significant correlation with that of Hmox1 in the tumor tissue of CRC." (PMID 27999449, 2016). "TCGA-A tumours showed higher expression of most group I/FTEC epithelial proteins such as KRT7, MSLN, CDH6, ASS1 and EPCAM, while TCGA-B tumours had higher expression of the group III/IOSE mesenchymal proteins ITGA5, HMOX1, SMTN and GJA1 (refs 7, 34)." (PMID 27561551, 2016). "In subjects with distant metastasis, the correlations between the mRNA levels of Nrf2 and Hmox1 were not significant in either the tumor or normal tissues." (PMID 27999449, 2016). "The correlations of Hmox1 with components of the Nrf2 pathway were not significant in the tumor tissue of CRC subjects with distant metastasis." (PMID 27999449, 2016). "The mRNA levels of Hmox1 and molecules of the Nrf2 pathway in either the tumor or normal tissues were not predictors for distant metastasis in CRC." (PMID 27999449, 2016).